CENPA (centromere protein A)
Diseases named in the same sentence as CENPA in open-access papers (continued):
Sharing a sentence is not in itself a finding about the gene and the disease.
glioma (continued). "In addition, high expression of CENPA suggested a poor prognosis in patients with primary and recurrent gliomas." (PMID 36341103, 2022). "In the current study, we extracted information on glioma from TCGA and CGGA databases to investigate whether CENPA can influence glioma progression and the potential mechanisms involved." (PMID 36341103, 2022). "GO and KEGG enrichment analyses were performed to further understand the biological processes involved in CENPA in gliomas and the pathways it may affect." (PMID 36341103, 2022). "CENPA was significantly upregulated in glioma tissue samples and correlated with patient prognosis." (PMID 36341103, 2022). "The CCK8 assay was performed to assess the role of CENPA in glioma cell proliferation." (PMID 36341103, 2022). "Combining the results of GSEA, GO analysis, and KEGG enrichment analysis, abnormal expression of CENPA may promote glioma progression by interfering with the normal process of mitosis." (PMID 36341103, 2022). "CENPA expression was found to be upregulated in glioma in this study." (PMID 36341103, 2022). "Similarly, qPCR and IHC results of samples obtained from our institute also support the high expression of CENPA in glioma samples." (PMID 36341103, 2022). "The results of GSEA, KEGG analysis, and GO enrichment analysis suggested that abnormal expression of CENPA in patients with glioma might affect the normal progression of mitosis and DNA repair, resulting in promoting glioma development." (PMID 36341103, 2022). "In addition, GSEA, KEGG analysis, GO analysis, and immune infiltration analysis were performed to explore the possible mechanisms between elevated CENPA expression and glioma progression." (PMID 36341103, 2022). "CENPA may act as a prognostic factor in patients with glioma and provide a novel target for the treatment of gliomas." (PMID 36341103, 2022). "Immunotherapy targeting CD276 may be effective in patients with glioma with high expression of CENPA." (PMID 36341103, 2022). "However, research on CENPA in malignant tumours such as glioma was relatively limited." (PMID 39620895, 2024). "However, the current study aims to explore whether aberrant CENPA expression promotes glioma progression and the potential mechanisms involved." (PMID 36341103, 2022). "Moreover, the downregulation of CENPA inhibited the migration and proliferation of glioma cells." (PMID 36341103, 2022). "Experiments in vivo revealed that high CENPA could promote glioma progression." (PMID 36341103, 2022). "CENPA, COL3A1, GRP65, SRPX2 and GPX8 were upregulated in glioma, while remaining genes were downregulated." (PMID 39620895, 2024). "Our experiments first verified the expression of CENPA in TCGA and CGGA databases, tissue samples and cell lines, confirming its upregulation in glioma tissues according to WHO grading." (PMID 39620895, 2024). "Furthermore, CENPA could serve as an independent prognostic factor for glioma that mainly interferes with the normal progression of mitosis and regulates the tumor immune microenvironment favoring glioma development." (PMID 36341103, 2022). "Regulating CENPA can affect functions of glioma, and these phenomena may act through the EZH2/CENPA/β‐catenin signalling axis." (PMID 39620895, 2024). "The negative correlation between CENPA and DCs and positive correlation between CENPA and Tregs indicate weaker anti-tumor immunity in patients with glioma with high CENPA expression." (PMID 36341103, 2022). "Notably, single-cell analysis of CENPA showed that CENPA and MKI67 are expressed in the same type of cells, mainly in glioma cells, suggesting that the high expression of CENPA means that the cells are in an active proliferative state." (PMID 36341103, 2022). "In addition, we found several hub genes with worse OS and higher expression level in glioma patients, including VEGFA, NDC80, TIMP1, SAA1, CENPA, CENPF, and NCAPG and we firstly found relationship of SAA1, TIMP1, and molecular pathology in GBM." (PMID 30867991, 2019).
glioma (continued). "Results of both enrichment and single-cell analyses indicated that mitosis was more intense in glioma cells from patients with glioma with high CENPA expression, which may explain the negative correlation between patient survival and CENPA expression." (PMID 36341103, 2022).
clear cell renal cell carcinoma (7 papers, 2021 to 2025). "Recent studies have confirmed that CENPA is highly expressed in clear cell renal cell carcinoma (KIRC) and is associated with poor prognosis as a biomarker." (PMID 41589308, 2025). "We constructed a multi-gene risk prediction model incorporating IGF2BP3, CENPA, and MEF2B to evaluate the prognostic predictive power of these three key genes in clear cell renal cell carcinoma (KIRC)." (PMID 41589308, 2025). "For example, CENPA can accelerate the cell cycle by triggering the Wnt/β-catenin pathway in clear cell renal cell carcinoma (ccRCC) cells." (PMID 37928273, 2023). "Another bioinformatic analysis identified CENPA as one of the prognostic-related GRGs in clear cell renal cell carcinoma." (PMID 35924040, 2022). "Experiments have verified that CENPA overexpression contributed to the proliferation and metastasis of clear cell renal cell carcinoma by accelerating the cell cycle and activating the Wnt/β-catenin signaling pathway." (PMID 36341390, 2022).
liver cancer (6 papers, 2020 to 2025). An epithelial or non-epithelial malignant neoplasm that arises from the liver. "The immune association of CENPA in certain cancer types, such as lung and liver cancer, has been previously demonstrated using TCGA data." (PMID 39820192, 2025). "The model of SPP1 combined with centromere protein A (CENPA), melanoma-associated antigen family member B6 (MAGEB6), and homeobox D9 (HOXD9) can predict the overall survival in liver cancer patients." (PMID 38374893, 2024). "Among them, MCODE 1 mainly comprised the mutations of CDK1, KIF2C, KIF18A, CENPA, and PLK1, which take part in the tumorigenesis and progression of liver cancer." (PMID 34414037, 2021). "In HPA database, we identified the CENPA protein expression in liver cancer." (PMID 32337237, 2020).
retinoblastoma (5 papers, 2021 to 2023). A malignant tumor that originates in the nuclear layer of the retina. "In summary, our study identifies a regulatory axis NRMT/CENPA/Myc/Bcl2 implicated in the resistance to CDDP in retinoblastoma cells, which contributes to the comprehensive understanding of molecules and pathways that control CDDP-induced apoptosis." (PMID 35013138, 2022). "Subsequently, our study evidenced that NRMT repressed the chemosensitivity of retinoblastoma cells by elevating the expression of CENPA." (PMID 35013138, 2022). "Importantly, aberrant expression of the NRTM/CENPA/Bcl2 axis developed in cisplatin (CDDP) resistance of retinoblastoma cells." (PMID 36012427, 2022). "Furthermore, CENPA induces the transcription of Myc and elevates the expression of Bcl2 in retinoblastoma cells." (PMID 36012427, 2022). "Above results suggested that NRMT could promote CENPA expression in retinoblastoma cells." (PMID 35013138, 2022). "Next, EdU assay indicated that overexpression of CENPA augmented the proliferation of cells, while inhibiting NRMT reversed the effect of CENPA on the proliferation of retinoblastoma cells." (PMID 35013138, 2022). "Rescue experiments suggested that CENPA reduced chemosensitivity by increasing the viability and proliferation and reducing apoptosis of CDDP-resistant retinoblastoma cells, which was reversed by NRMT." (PMID 35013138, 2022). "The results of flow cytometry and western blot analysis showed that overexpression of CENPA inhibited the apoptosis of cells, whereas NRMT silencing counteracted the effect of CENPA on the apoptosis of retinoblastoma cells." (PMID 35013138, 2022). "At last, our in vivo experimental data confirmed the downregulation of CENPA/Myc/Bcl2 by NRMT silencing, which possibly could be the mechanism responsible for the enhanced chemosensitivity of retinoblastoma cells." (PMID 35013138, 2022). "Particularly, TPX2, KIF20A, CENPA, DLGAP5, and LMNB1 of HHOs were significantly enriched by the retinoblastoma (RB) immunity downregulating PD-L1 expression pathway." (PMID 37240068, 2023).
bladder cancer (4 papers, 2021 to 2025). "Knockdown of CENPA in bladder cancer cells significantly decreased cell proliferation and migration." (PMID 40804263, 2025). "Based on the insights provided by previous findings, we sought to further explore the potential involvement of CENPA in bladder cancer development." (PMID 40804263, 2025). "This study is the first to reveal the therapeutic potential of recombinant MAP30 in bladder cancer and identifies CENPA as a novel downstream target mediating its antitumor effects." (PMID 40804263, 2025). "The EdU cell proliferation assay showed that knockdown CENPA with shRNA transfection can significantly decrease the EdU-positive ratio of bladder cancer cells." (PMID 40804263, 2025). "By integrating transcriptomic, proteomic, and functional analyses, we demonstrate that MAP30 suppresses bladder cancer progression through CENPA downregulation, linking cell cycle regulation, apoptosis, senescence, and immune modulation." (PMID 40804263, 2025). "In conclusion, recombinant MAP30 effectively hampers bladder cancer cell proliferation and migration via CENPA downregulation and induces apoptosis and senescence, offering therapeutic potential against bladder cancer." (PMID 40804263, 2025). "For the patient’s prognosis, the results show that CENPA contributes to the worse outcome of bladder cancer in both GSE5287 and TCGA-BLCA datasets." (PMID 40804263, 2025). "However, studies investigating the role of CENPA in the progression of bladder cancer remain limited." (PMID 40804263, 2025). "Also, CENPA was found high expressed in muscle-invasive bladder cancer based on the GSE13507 dataset and in high histologic-grade bladder cancer based on the TCGA-BLCA dataset." (PMID 40804263, 2025). "Furthermore, based on PPI analysis, we identified the key molecule CENPA that MAP30 inhibits bladder cancer." (PMID 40804263, 2025). "In conclusion, momordica charantia MAP30 can significantly inhibit the proliferation and migration of bladder cancer cells by downregulating the expression of CENPA and can promote cell apoptosis and cancer cellular senescence, thus playing a role in the treatment of bladder cancer." (PMID 40804263, 2025). "CENPA, one of the key nodes in cluster 1, was considered the key gene MAP30 regulated, and it was found downregulated in MAP30-treated bladder cancer cells and tumors." (PMID 40804263, 2025). "The expression of CENPA was significantly lower in TCGA-BLCA and GSE3167 bladder cancer datasets." (PMID 40804263, 2025). "Levels of CDCA3, CENPF, CENPA and KIF4A are correlated in bladder cancer." (PMID 34905505, 2021). "In the CENPA knockdown cells, the epithelial marker CDH1 and cell senescence marker p21 were significantly upregulated, while the mesenchymal marker CDH2 was downregulated, while CENPA overexpression can significantly inhibit the damage of MAP30 to bladder cancer cells." (PMID 40804263, 2025).
endometrial carcinoma (4 papers, 2021 to 2025). A malignant tumor arising from the epithelium that lines the cavity of the uterine body. "Centromere protein A (CENPA) has emerged as a critical transcription factor in the regulation of glutamine metabolism in endometrial cancer (EC) cells." (PMID 41515893, 2025).
lung squamous cell carcinoma (4 papers, 2020 to 2025). "CircTP63, highly expressed in lung squamous cell carcinoma (LUSC) tissues and facilitated cell cycle progression by acting as an miR-873-3p sponge to upregulate the expression of FOXM1, CENPA and CENPB." (PMID 39519039, 2024). "In lung squamous cell carcinoma, circTP63 binds competitively to miR-873-3p and prevents it from suppressing FOXM1, thereby upregulating CENPA and CENPB and promoting cell cycle progression." (PMID 38191906, 2024).
pancreatic cancer (4 papers, 2017 to 2025). "CENPM, a component of the CENPA-nucleosome associated complex, has also been reported to be associated with liver and pancreatic cancers." (PMID 36635779, 2023). "To delve deeper into the influence of CENPA on the growth and migration of pancreatic cancer, we developed PANC-1 and MIA Paca-2 cell lines with CENPA knockdown." (PMID 39456925, 2024). "First, we investigated small molecule anti-tumor drugs related to the expression levels of the CENPA gene in multiple pancreatic cancer datasets through the BEST website." (PMID 39456925, 2024). "In our study, by utilizing CCK-8, wound-healing, and transwell migration experiments, we have ascertained that the downregulation of CENPA unequivocally hinders the proliferation and migratory potential of pancreatic cancer cells." (PMID 39456925, 2024). "Overall, our findings indicate that CENPA is not only a marker of poor prognosis in pancreatic cancer but also a potential therapeutic target." (PMID 39456925, 2024). "Furthermore, the relative high mRNA expression of CENPA in the PC cell line was found in our experiments, indicating the mechanism of CENPA in the tumorigenesis of pancreatic cancer worth investigation." (PMID 39456925, 2024). "Finally, further investigations are required to elucidate the complex molecular mechanisms through which the knockdown of CENPA suppresses pancreatic cancer proliferation and migration, especially in the context of hypoxic and high-lactate metabolic environments." (PMID 39456925, 2024).
Autoimmunity (3 papers, 2010 to 2024). The occurrence of an immune reaction against the organism's own cells or tissues. "CENPA expression and micronuclei formation correlate highly with activation of the cGAS-STING/IFN-β pathway as well as markers of reactive oxygen species (ROS) and fibrosis, ultimately suggesting a link between centromere alterations, chromosome instability, SSc autoimmunity, and fibrosis." (PMID 36400785, 2022).
breast tumors (3 papers, 2010 to 2011). "The PR gene, PGR, and 3 other genes (GATA3, STC2 and GLI3) are increased in their expression, whereas the expression of 6 genes (AURKA, BUB1, CDC20, MKI67, HJURP, and CENPA) is decreased in PR-positive breast tumors." (PMID 22022496, 2011).
invasive breast carcinoma (3 papers, 2012 to 2022). A carcinoma that infiltrates the breast parenchyma. "Increased CENPA showed weak association with DFS in invasive breast cancer." (PMID 32337237, 2020). "In this same cohort we have reported a significant increase in expression of Centromere Protein-A (CENPA) expression in invasive breast cancers compared to normal breast tissues using bivariate analysis of continuous data." (PMID 24213463, 2012).
neuroblastoma (3 papers, 2014 to 2025). Neuroblastoma (NB) is the most common solid, extracranial childhood tumor. "A majority of FOXM1 target genes, including CDC25B, CHEK2, CENPA, CENPB, and CENPF, were significantly downregulated in neuroblastoma cells with MEIS2 depletion." (PMID 25210800, 2014).
renal cell carcinoma (3 papers, 2022 to 2025). "As a representative member of the centromere protein (CENP) family, CENPA overexpression has also been shown to drive renal cell carcinoma proliferation and metastasis by accelerating the cell cycle and activating the Wnt/β-catenin signaling pathway." (PMID 40804263, 2025). "In vitro studies have also shown that CENPA can activate the Wnt/β-catenin signaling pathway and promote the proliferation and metastasis of renal cell carcinoma." (PMID 35938165, 2022).
scleroderma (3 papers, 2009 to 2024). Scleroderma is a rare autoimmune connective tissue disorder characterized by abnormal hardening of the skin and, sometimes, other organs. "CENPA is an 18-kDa protein firstly identified in humans by autoantibodies found in patients suffering scleroderma." (PMID 20119530, 2009). "Autoantibodies against CENPA and CENPB are primarily found in patients suffering limited systemic sclerosis or scleroderma." (PMID 20119530, 2009).
autoimmune disease (2 papers, 2010 to 2021). A disorder resulting from loss of function or tissue destruction of an organ or multiple organs, arising from humoral or cellular immune responses of the individual to their own tissue constituents. "To test the generalizability of the method in an additional autoimmune disease, we identified and validated autoantigenic signals to SSB, CENPA, and keratin proteins in a cohort of individuals with Sjogren’s syndrome (n=91)." (PMID 33986742, 2021).
breast adenocarcinoma (2 papers, 2020). "Notably, CENPA, FOXM1, and MYBL2 are also key regulators of cancer-specific enhancers in breast adenocarcinoma of the basal subtype, but they are associated with distinct sets of activated enhancers." (PMID 32925947, 2020).
cholangiocarcinoma (2 papers, 2017 to 2020). A carcinoma that arises from the intrahepatic biliary tree (intrahepatic cholangiocarcinoma) or from the junction, or adjacent to the junction, of the right and left hepatic ducts (hilar cholangiocarcinoma). "The analysis of samples in our cohort also showed that the degree of downregulation of the miR-204 and of some of its targets (SHCBP1, CENPA, RAD51) was higher in the intrahepatic cholangiocarcinoma samples as opposed to the extrahepatic ones." (PMID 28199974, 2017).
chromophobe renal cell carcinoma (2 papers, 2020 to 2025). Chromophobe renal cell carcinoma is a rare subtype of renal cell carcinoma, originating from the intercalating cells of the collecting ducts and macroscopically manifesting as a well-circumscribed, highly lobulated, solid tumor that is usually diagnosed at an early stage. "Moreover, only the hub gene CENPA is related to overall survival, which may be a novel biomarker involved in chromophobe renal cell carcinoma." (PMID 32090070, 2020).
COVID-19 (2 papers, 2022 to 2024). A disease caused by infection with severe acute respiratory syndrome coronavirus 2. "Similarly, we found the relevant evidence of alteration or association of transcription factors CENPA, DDIT3, JUNB, TFDP1, ZBTB16, ZNF467 for the alteration of diverse cellar process and function to develop the COVID-19 pathogenesis and associated respiratory disorders." (PMID 38365632, 2024).
metastatic prostate carcinoma (2 papers, 2020 to 2026). A carcinoma that arises from the prostate gland and has spread to other anatomic sites. "CENPA is infrequently mutated and amplified in metastatic prostate cancer." (PMID 32371391, 2020). "Importantly, receiver operator characteristic analysis of the CENPA-stained prostate tissue microarray produced an area under the curve of 0.89, orthogonally demonstrating a strong association between elevated CENPA expression and metastatic prostate cancer." (PMID 32371391, 2020).
renal carcinoma (2 papers, 2021 to 2022). A carcinoma arising from the epithelium of the renal parenchyma or the renal pelvis. "Notably, CENPA overexpression was also associated with proliferation and metastasis in kidney carcinoma by activating the WNT/β-Catenin signaling pathway, an important pathway described in the progression of ACC." (PMID 36358698, 2022). "Our effort disclosed that CENPA is an important renal cancer biomarker and a possible highly specific therapeutic target." (PMID 34627268, 2021). "Further studies may elucidate whether the relationship in renal carcinoma between CENPA activity and the WNT/β-Catenin signaling pathway may apply to ACC." (PMID 36358698, 2022).
thymoma (2 papers, 2022 to 2025). A neoplasm arising from the epithelial cells of the thymus. "The results revealed that CENPA was significantly associated with worse overall survival in 13 cancer types, while it was linked to better overall survival in one cancer type, thymoma (THYM)." (PMID 39820192, 2025).